ARNT (aryl hydrocarbon receptor nuclear translocator)
Diseases named in the same sentence as ARNT in open-access papers (continued):
Sharing a sentence is not in itself a finding about the gene and the disease.
type 2 diabetes (8 papers, 2008 to 2024). "We hypothesized that common polymorphisms in the ARNT gene might increase the susceptibility to type 2 diabetes through impaired glucose-stimulated insulin secretion." (PMID 18366646, 2008). "Intriguingly, reduced HIF-1α and HIF-1β/ARNT expression has been observed in the islets of type 2 diabetic patients." (PMID 38673770, 2024). "With regard to ARNT, expression decreases in the liver and pancreatic islets of patients with type 2 diabetes, and deletion of ARNT in these tissues results in impairment of metabolism." (PMID 31800592, 2019). "Recent studies have highlighted the critical role of ARNT in energy homeostasis in major endocrine organs, and consequently in the pathogenesis of type II diabetes." (PMID 28005939, 2016). "ARNT expression is dramatically down-regulated in pancreatic islets from humans with type II diabetes." (PMID 28005939, 2016). "ARNT (also called as HIF-1β) is expressed in islets, and is decreased in islets from humans with type 2 diabetes." (PMID 24878748, 2014). "We have previously shown that the expression of the transcription factor ARNT (Aryl-hydrocarbon Receptor Nuclear Translocator) is reduced in the islets of humans with type 2 diabetes." (PMID 24204824, 2013). "We have previously reported that the transcription factor ARNT is reduced in islets of humans with type 2 diabetes." (PMID 24204824, 2013). "The ARNT gene is located on human chromosome 1q21.2, a region with well replicated linkage to type 2 diabetes by us in European American and African American populations, and by others in European American, Chinese, and Pima Indian populations." (PMID 18366646, 2008). "A further role of ARNT in type 2 diabetes is suggested by its role as an obligate partner of several transcription factors involved in the response to toxins and hypoxic stress." (PMID 18366646, 2008). "Similarly, in human T2D islets, reduced ARNT expression is associated with a reduction in expression of glucose metabolic genes including IRS2, IR, AKT2, G6PI, PFK, PGM and the maturity onset diabetes of the young (MODY) gene HNF-4α." (PMID 24204824, 2013). "ARNT, a member of the basic helix-loop-helix family of transcription factors, is located on human chromosome 1q21–q24, a region which showed well replicated linkage to type 2 diabetes." (PMID 18366646, 2008). "Thus, in addition to being a strong functional candidate, ARNT is a strong positional candidate gene for type 2 diabetes." (PMID 18366646, 2008). "In addition to data supporting ARNT as a strong functional candidate gene for type 2 diabetes, the ARNT gene is located on human chromosome 1q21, a region with replicated linkage to type 2 diabetes in diverse populations." (PMID 18366646, 2008). "We previously reported ARNT (Aryl-hydrocarbon Receptor Nuclear Translocator, also called hypoxia inducible factor 1β (HIF-1β)) to be a susceptibility factor for beta-cell dysfunction and type 2 diabetes (T2D)." (PMID 24204824, 2013). "Surprisingly, the impact of ARNT signaling in the skeletal muscles, one of the major organs involved in glucose disposal, has not been investigated, especially in type II diabetes." (PMID 28005939, 2016).
renal cell carcinoma (7 papers, 2010 to 2025). "The upregaulted gene ARNT is invovled in Hypoxia Signaling in the Cardiovascular System, Renal Cell Carcinoma Signaling, VEGF Signaling, HIF1α Signaling, Aryl Hydrocarbon Receptor Signaling and Xenobiotic Metabolism Signaling pathways." (PMID 33272211, 2020).
colorectal cancer (6 papers, 2014 to 2023). A primary or metastatic malignant neoplasm that affects the colon or rectum. "In this study, we investigated the roles of ARNT in the function of CD11b+Gr1+ neutrophils in colitis-associated colorectal cancer." (PMID 36859266, 2023). "In summary, we found that ARNT governs the recruitment and functional activities of regulatory neutrophils and modulates the alteration of the gut microbiota in colitis-associated colorectal cancer pathological microenvironments." (PMID 36859266, 2023). "Our study demonstrates that the loss of ARNT induces a cascade of events, which results in a pro-metastatic phenotype in colorectal cancer." (PMID 25839165, 2015). "Collectively, these results suggest that neutrophils play a crucial role in the development and growth of colorectal cancer through ARNT signaling." (PMID 36859266, 2023). "Next, we examined ARNT expression in colorectal cancer specimens using immunohistochemical staining." (PMID 25839165, 2015). "Consistent with our finding that ARNT was decreased in late-stage colorectal cancer, miR-107 is elevated in highly metastatic colorectal cancer tissue." (PMID 25839165, 2015). "In human colorectal cancer, downregulation of the aryl hydrocarbon receptor nuclear translocator (ARNT or HIF-1β) promoted cancer cell migration and invasion through the activation of the fibronectin/β1 integrin/FAK signaling axis." (PMID 26635609, 2015). "Analysis of a dataset from GEO that contained 58 colorectal carcinomas also showed decreased ARNT expression in late-stage human colorectal cancer." (PMID 25839165, 2015). "We demonstrated a clinically relevant correlation between ARNT down-regulation and late-stage colorectal cancer." (PMID 25839165, 2015). "Here, we demonstrate that ARNT protein levels were decreased in late-stage human colorectal cancer using immunohistochemical analysis." (PMID 25839165, 2015). "In the present study, we established that an underappreciated function of the transcription factor ARNT in colorectal cancer is to limit the recruitment and function of neutrophils coupled with the gut microbiota to enable colitis-associated colorectal cancer progression." (PMID 36859266, 2023). "Next, we sought to apply a pharmacological approach to target ARNT in neutrophils and determine its effects on neutrophil function and colorectal cancer development to test whether we can recapitulate our findings from genetically targeting ARNT." (PMID 36859266, 2023). "Therefore, CXCR2 signaling is required for ARNT-directed neutrophil recruitment and function while contributing to colorectal cancer development and growth." (PMID 36859266, 2023). "Our results defined a new role for the transcription factor ARNT in regulating neutrophils recruitment and function and the gut microbiota with implications for the future combination of gut microbiota and immunotherapy approaches in colorectal cancer." (PMID 36859266, 2023). "Importantly, in colorectal cancer mice, the expression of ARNT was highest in tumor-infiltrating neutrophils among various immune-infiltrating cells." (PMID 36859266, 2023). "The database search also revealed that ARNT was amplified in 36% of all the cancers analyzed (q value = 1.61 × 10−49) and, importantly, that it mapped to a peak of amplification present in almost 13% of colorectal cancers." (PMID 25839165, 2015). "In addition, ARNT expression was negatively correlated with cancer stage in human colorectal cancer." (PMID 25839165, 2015). "ARNT expression was significantly down-regulated in late-stage human colorectal cancer." (PMID 25839165, 2015). "Furthermore, ARNT expression was inversely correlated with cancer stage in human colorectal cancer." (PMID 25839165, 2015).
glioma (6 papers, 2012 to 2024). A benign or malignant brain and spinal cord tumor that arises from glial cells (astrocytes, oligodendrocytes, ependymal cells). "Analysis of public datasets revealed ARNT is upregulated in GBM tissues compared to lower grade gliomas or normal brain tissues." (PMID 38806469, 2024). "Collectively, these findings underscore the critical role of ARNT in GBM tumorigenesis, both in vivo and in vitro, and highlight that silencing ARNT mitigates the malignancy of glioma cell lines." (PMID 38806469, 2024). "Moreover, we identified that elevated ARNT expression closely correlated with poor prognosis in glioma patients." (PMID 38806469, 2024). "Therefore, to confirm the role of ARNT in glioma, ARNT mRNA expression was analyzed across different molecular subtypes using TCGA datasets." (PMID 38806469, 2024). "ARNT was upregulated in the mesenchymal subtype of glioma, indicating that ARNT may serve as a regulator of chemoresistance." (PMID 38806469, 2024). "Both ARNT and p38α expression were markedly elevated in 1763 and U251MG glioma cell lines (ARNT was overexpressed as indicated) in response to CoCl2." (PMID 38806469, 2024). "The results revealed a significant increase in ARNT expression in glioblastoma (GBM) compared to low-grade glioma or non-brain tumor tissues." (PMID 38806469, 2024).
leukemia (6 papers, 2014 to 2025). A malignant (clonal) hematologic disorder, involving hematopoietic stem cells and characterized by the presence of primitive or atypical myeloid or lymphoid cells in the bone marrow and the blood. "This conclusion corroborates a similar finding of the antioxidant role of ARNT previously observed in leukemia." (PMID 34179020, 2021). "Resistant leukemia cells exhibited an abundance of ARNT and also followed upregulation of SODs (SOD2), nuclear factor erythroid 2-related factor 2 (Nrf2) transcript, and intracellular glutathione concentration." (PMID 24921657, 2014). "In particular, ARNT (Aryl Hydrocarbon Receptor Nuclear Translocator) is a nuclear receptor which has been demonstrated to enhance antioxidant response and to confer drug resistance in leukemia cells." (PMID 27683112, 2016). "However, ARNT fusion products have been described in leukemias, including AML." (PMID 33544756, 2021).
liver fibrosis (6 papers, 2015 to 2026). "Analysis of hepatic transcriptional profiles of MCD and GNMTKO mice reveals novel association of the transcriptional regulators STAT5b, AhR, and ARNT with liver fibrosis." (PMID 41519232, 2026). "The inhibition of FKBP12/YY1 increased ARNT expression, reducing organ damage in renal, heart, and liver fibrosis models." (PMID 37508425, 2023). "In the present study hepatocyte specific ARNT-null (LARNT) mice were created to investigate the role of hepatocyte ARNT in liver fibrosis." (PMID 25812120, 2015). "Deletion of hepatocyte ARNT leads to altered expression of collagen associated mRNA and reduced macrophage infiltration in the TAA-induced model of liver fibrosis." (PMID 25812120, 2015). "In murine models of kidney fibrosis, and also of liver fibrosis, combinations of FK506 or GPI1046 (to induce ARNT expression) with LB100 (to enhance ARNT homodimerization) elicit additive anti-fibrotic activities." (PMID 34912030, 2021).
prostate carcinoma (6 papers, 2006 to 2023). A carcinoma that arises from epithelial cells of the prostate gland. "By contrast, little attention has been paid to the effects on ARNT/TACC3 axis in prostate cancer." (PMID 37292153, 2023). "Because E2F3 interact with ARNT, we can infer the interactions between two dependent genes AKT3 and CHUK and map to their gene products, protein PKB and IKK in prostate cancer pathway." (PMID 20025723, 2009).
cervical cancer (5 papers, 2012 to 2025). A primary or metastatic malignant neoplasm involving the cervix. "The increased expression of ARNT in cervical cancer suggests that the tumor is responding to its microenvironment, facilitating processes like angiogenesis and metabolic changes that support tumor survival and growth." (PMID 40438679, 2025). "The analysis of the TCGA data by the GEPIA webtool revealed the strong positive correlation between AhR and Notch1 (R = 0.39, p = 2.5 × 10−12) and between ARNT and Notch1 (R = 0.54, p = 0) in cervical cancer patients." (PMID 32545442, 2020). "This suggests that the inhibition of AhR/ARNT activity is potentially developed as a therapeutic strategy for cervical cancer." (PMID 32545442, 2020). "Therefore, we expected that knockdown of ARNT in ECC-1 endometrial-cervical cancer cells would result in a diminution of ER target gene expression." (PMID 22235307, 2012). "In our previous studies, we found that ARNT interacted with c-Jun to form c-Jun/ARNT and c-Jun/ARNT/Sp1 complexes which promote expressions of cyclooxygenase (COX)-2, 12(S)-lipoxygenase, and p21WAF1/CIP1, in epidermal growth factor (EGF)-treated cervical cancer cells in a normoxic condition." (PMID 24921657, 2014).
coronary artery disease (4 papers, 2017 to 2023). "By examining these aspects, we hope to shed light on the pathogenesis of ischemic heart disease and explore the potential of targeting HIF2α and ARNT in endothelial cells as promising new approaches for treating IHD." (PMID 37508425, 2023). "During hypoxia, HIF2α/ARNT signaling activation is particularly vital in heart endothelial cells, as it promotes angiogenesis, regulates inflammation, maintains the endothelial barrier integrity, and prevents ischemic heart disease development and progression." (PMID 37508425, 2023). "In addition, this review aims to enhance the current knowledge of HIF2α and ARNT signaling in endothelial cells and their potential as therapeutic targets for ischemic heart disease." (PMID 37508425, 2023). "For instance, allele rs55730499-T associated with increased level of LDL-C and the risk of coronary artery disease was predicted to create binding sites for transcription factors acting as activators (NR1H, AHR::ARNT, IRF) or repressors (HAND1) of gene expression." (PMID 35203469, 2022). "Therefore, endothelial cell-specific ARNT expression is crucial for angiogenesis and may protect against ischemic heart diseases." (PMID 37508425, 2023). "After intersection of AHR with ARNT and TCF21 the only remaining categories were coronary artery disease and coronary artery calcification, narrowing the importance of the interaction of AHR/ARNT and TCF21 factors to pathophysiological processes in cardiovascular disease." (PMID 28481916, 2017).
multiple myeloma (4 papers, 2018 to 2024). "The HIF-β subunits, also known as aryl hydrocarbon nuclear translocators (ARNT), are not regulated by any changes in oxygen, although a study on high-risk multiple myeloma cells shows that chronic hypoxia increases HIF-1β expression via NF-κB." (PMID 34639040, 2021). "Mechanically, ARNT mediates the proliferation of myeloma cells and drug resistance through the AKT signaling pathway; in addition, ARNT, as an autophagy-related gene, has a potential relationship with hypoxia, metabolism, and immunity in the bone marrow microenvironment of MM patients." (PMID 38831978, 2024).
neuroblastoma (4 papers, 2009 to 2024). Neuroblastoma (NB) is the most common solid, extracranial childhood tumor. "Through the development of selective small-molecule inhibitors targeting HIF2α/ARNT dimerization, potentially suitable drugs are available, which are of particular interest for the more aggressive pseudohypoxic PPGLs and neuroblastomas." (PMID 37361539, 2023). "Similar to observations in PPGLs, ARNT-dependent inhibition of HIF2α by PT2385 (HIF2α inhibitor) is not sufficient to regulate HIF2α downstream target genes in neuroblastoma, which also indicates a ARNT-independent mechanisms of HIF2α in neuroblastoma (see discussion above)." (PMID 37361539, 2023).
ovarian carcinoma (4 papers, 2012 to 2024). A malignant neoplasm originating from the surface ovarian epithelium. "We found that 8 of our 93 regions contained such types of genes, nine in total, including AKT1, ARNT, PMS2, and the oncogenic ubiquitin hydrolase, DUB3 for which we previously reported abnormal demethylation in our integrated study of ovarian cancer." (PMID 23293768, 2012).
colitis (3 papers, 2018 to 2024). Inflammation of the colon. "Given that LTB4 has been shown to exacerbate colitis, its increase in LysMCre;Arntfl/fl colons reinforced the observation that myeloid ARNT deficiency resulted in a more inflamed colonic microenvironment." (PMID 30455703, 2018). "Collectively, these data suggest that myeloid ARNT is required for proper resolution of acute colitis." (PMID 30455703, 2018). "In this study, we found that ARNT deficiency in neutrophils, drives their recruitment, neutrophil extracellular trap (NET) formation, inflammatory cytokine secretion and suppressive activities in a gut microbiota-dependent manner in colitis-associated tumorigenesis." (PMID 36859266, 2023). "By depleting ARNT (the obligate heterodimeric binding partner for both HIFα subunits) in a murine model, we demonstrate here that myeloid HIF signaling promotes the resolution of acute colitis." (PMID 30455703, 2018). "Our findings suggest that myeloid AhR is not likely a major contributor to colitis resolution, as disruption of HIF-1α and HIF-2α signaling accounts for the majority of ARNT-dependent effects in our model." (PMID 30455703, 2018).
endometriosis (3 papers, 2024 to 2025). The growth of functional endometrial tissue in anatomic sites outside the uterine body. "Abnormal activation of AHR and the aryl hydrocarbon receptor nuclear translocator (ARNT) is common in endometriosis and uterine leiomyoma." (PMID 38752181, 2024). "In certain pathological conditions, such as endometriosis, uterine leiomyomas, and presumably PCOS, mRNA expression of transcription factors AHR and ARNT is altered at select target sites." (PMID 38468402, 2024).
fatty liver (3 papers, 2014 to 2019). "ARNT may down-regulate fatty liver disease induction by the aryl hydrocarbon receptor." (PMID 31800592, 2019).
Hypertension (3 papers, 2021 to 2024). The presence of chronic increased pressure in the systemic arterial system. "We observed that high-dose RBE that protected offspring against hypertension coincided with decreased renal expression of ARNT and AHR downstream of the target gene CYP1A1." (PMID 36771404, 2023). "This is supported by the present observations, which demonstrated that CKD-induced hypertension coincides with the activation of the AhR signaling pathway as represented by increased ARNT and TIPARP expression." (PMID 35052587, 2021). "In a rat model of maternal BPA exposure, adult offspring developed hypertension alongside increased protein levels of AHR and mRNA expression of AHRR, CYP1A1, and ARNT in the offspring kidneys." (PMID 38731818, 2024). "In a maternal DEHP exposure model, low-dose RBE treatment significantly shielded adult rat offspring against hypertension, accompanied by a reduction in renal mRNA expression of CYP1A1 and ARNT." (PMID 38731818, 2024).
Insulin resistance (3 papers, 2013 to 2021). Increased resistance towards insulin, that is, diminished effectiveness of insulin in reducing blood glucose levels. "Manipulation of ARNT expression in various organs relevant to energy homeostasis such as pancreas, liver and adipose tissues influenced glucose intolerance and insulin resistance." (PMID 28005939, 2016). "Aryl Hydrocarbon Receptor Nuclear Translocator/ hypoxia-inducible factor 1 beta (ARNT/ HIF1β), a member of bHLH-PAS family of transcriptional factors, plays a critical role in metabolic homeostasis, insulin resistance and glucose intolerance." (PMID 28005939, 2016). "ARNT reduction in MVECs was observed in both types 1 and 2 diabetic mouse models, suggesting that hyperglycemia, rather than insulin resistance, impairs endothelial ARNT activity." (PMID 34179020, 2021). "We have previously reported that islet ARNT expression is not altered in models of insulin resistance including the ob/ob and db/db mouse." (PMID 24204824, 2013).
kidney cancer (3 papers, 2019 to 2023). Primary or metastatic malignant neoplasm involving the kidney. "ARNT, CTCF, POLR2A, RAD21 and REST were downregulated in kidney cancer samples and indicated poor prognosis when lowly expressed, which revealed that ARNT, CTCF, POLR2A, RAD21 and REST tended to be risk factors with lower gene expression." (PMID 31727869, 2019). "Therefore, therapies that block HIF-2 dimerization can release more HIF-1β/ARNT to bind with AHR, thereby potentially promoting the oncogenic effects of the AHR pathway in kidney cancer." (PMID 36725335, 2023).